HDAC3 (histone deacetylase 3)
Diseases named in the same sentence as HDAC3 in open-access papers (continued):
Sharing a sentence is not in itself a finding about the gene and the disease.
breast cancer (continued). "Altogether, our findings reveal an EGF signaling cascade involving EGFR, c-Src, and HDAC3 in breast cancer cells." (PMID 31430896, 2019). "Our findings identify the activation mechanism of HDAC3 and propose a new therapeutic target for the treatment of breast cancer." (PMID 31430896, 2019). "The invasiveness of breast cancer cells decreased in the c-Src knocked down sh-Control and sh-HDAC3 infected cells." (PMID 31430896, 2019). "HDAC3 inhibition with either c-Src knockdown or PP2 treatment significantly ameliorated the invasiveness of breast cancer cells." (PMID 31430896, 2019). "At the same time, our results support the previous reports, highlighting the importance of HDAC3 selective inhibition in the regulation of breast cancer." (PMID 31430896, 2019). "The present study has not indicated the exact molecular mechanism involved in either the changes in the subcellular localization of HDAC3 or the regulation of invasion of breast cancer cells." (PMID 31430896, 2019). "We previously reported the involvement of HDACs (HDAC2 and HDAC3) in KCa3.1 transcription in human breast cancer cells." (PMID 30262728, 2018). "We previously reported epigenetic modifications to KCa3.1 by HDAC2 and HDAC3 in human breast cancer cells." (PMID 30262728, 2018). "HDAC3 (ranked 2nd for breast cancer) is a histone deacetylase (HDAC), a family of enzymes that regulates gene expression by interacting with histones." (PMID 29017547, 2017). "In doing so, the expression level of Nav1.5, nNav1.5, REST, HDAC1, HDAC2, and HDAC3 were measured and compared between the less aggressive human breast cancer cells, MCF-7 and the aggressive, MDA-MB-231 cells." (PMID 28785170, 2017). "The expression patterns of HDAC1, HDAC2, and HDAC3 have been evaluated in different types of cancers, including gastric cancer, liver cancer, prostate cancer, breast cancer, renal cell cancer, ovarian and endometrial carcinomas." (PMID 28785170, 2017). "This study focused on examining the role of REST, HDAC1, HDAC2, and HDAC3 on influencing the expression of Nav1.5 and nNav1.5 in breast cancer that promote aggressiveness." (PMID 28785170, 2017). "In our previous study, the pharmacological and siRNA-mediated blockade of HDAC2 or HDAC3 resulted in the down-regulation of the intermediate-conductance Ca2+-activated K+ channel KCa3.1 in human breast cancer YMB-1 cells." (PMID 27973439, 2016). "An example of a protein-coding gene downregulated in breast cancer with a non-coding antisense transcript significantly upregulated in breast cancer versus normal tissue is HDAC3 (histone deacetylase 3) on chr5." (PMID 25264628, 2014). "It was previously reported that knockdown of HDAC3 decreased estrogen-dependent MCF-7 breast cancer cell proliferation." (PMID 25521755, 2014). "On the other hand, studies reported that HDAC3 is an inhibitor of migration of metastatic breast cancer cells." (PMID 25264628, 2014). "Our study demonstrates a differential expression of HDAC1, HDAC2 and HDAC3 using immunohistochemistry in breast cancer." (PMID 23627572, 2013). "This suggests that HDAC3 plays a key role in the development and progression of brain metastases in breast cancer patients, though the study did not explore the underlying mechanisms in detail." (PMID 40260239, 2025). "HDAC2 is associated with poor survival and relapse of cancer, HDAC3 promotes oncogenesis and is a good target for therapeutics, HDAC5 is known to increase the stemness of breast cancer cells, and HDAC7 protein is associated with reoccurrence of breast cancer." (PMID 40426890, 2025). "In an organoid-based study of breast cancer, the use of adenovirus to block the interaction of HDAC3 with nuclear receptor co-repressor 2 (NCOR2) was found to up-regulate the expression of interferon regulatory factor 1 (IRF-1) and interferon-γ (IFN-γ) factors." (PMID 40006729, 2025).
breast cancer (continued). "Importantly, only in breast cancer has it been indicated that suppression of HDAC3 expression can downregulate ERα, a protective factor in breast cancer, but this has not been reported in liver cancer." (PMID 37752418, 2023). "The results indicate a positive role of HDAC3 in enhancing AI resistance of ER+ breast cancer." (PMID 37414914, 2023). "More importantly, our findings suggest that decreased SERPINA3 as well as increased ANKRD11 expression as biomarkers that may predict the efficiency of HDAC3 inhibitor in treating AI-resistant breast cancer." (PMID 37414914, 2023). "This study identified a HDAC member, HDAC3, as a downstream target of ERα pathway that contributes to AI resistance in ER+ breast cancer, which may provide explanations for the contradictory results between clinical trials ACE and E2112." (PMID 37414914, 2023). "This study provides the rationale to investigate whether effective HDAC3 inhibitors can improve the anti-tumor activities of AIs in endocrine-resistant breast cancer patients with upregulated ANKRD11 expression." (PMID 37414914, 2023). "Whether effective HDAC3 inhibition is sufficient to provide additional benefits with AI therapy in endocrine-resistant breast cancer is a question worth further clinical assessment." (PMID 37414914, 2023). "GGT1 has a suggested function in pancreatic carcinogenesis, whereas NCOR1 is part of a corepressor complex with histone deacetylase 3 (HDAC3) and may act as an oncogene in thyroid cancer, while ERCC5 polymorphisms were reported in breast cancer." (PMID 35205822, 2022). "Therefore, HDAC3 acts as an independent prognostic biomarker for brain metastasis-free survival in breast cancer patients." (PMID 35110603, 2022). "HDAC3 is strongly expressed in a subgroup with more aggressive breast cancer." (PMID 36077333, 2022). "In consistency with our study, geminin‐associated HDAC3 has been proposed to deacetylate FOXO3 to inhibit its transcriptional activity, thus inhibiting downstream FOXO3 target Dicer, an essential RNase to inhibit metastasis of breast cancer cell." (PMID 33655712, 2021). "Since HDAC1, HDAC2, and HDAC3 are the most common histone deacetylases in human tissues with a relatively high abundance and have already been reported elsewhere to be potential oncogenes in breast cancer, our studies mainly focus on these three HDAC proteins." (PMID 32686908, 2020). "To identify whether histone deacetylases have direct relationships with the prognosis of breast cancer patients, we assessed the HDAC1, HDAC2, and HDAC3 protein expression data from a combined cohort of 161 breast cancer cases." (PMID 32686908, 2020). "Thus, HDAC1, HDAC2, and HDAC3 all displayed typical oncogenic characteristics and were important in the early development of breast cancer and later survival of patients." (PMID 32686908, 2020). "Our study demonstrated a possible mechanism mediated by HDAC3 in breast cancer cells." (PMID 32455774, 2020). "Our studies first demonstrate a critical role for HDAC3 in the brain metastasis of breast cancer patients and it may serve as a promising therapeutic target for the vigorously developing field of precision medicine." (PMID 32686908, 2020). "Another possible reason is that the sample size of our study is still relatively small; if more breast cancer patients with brain metastasis are included, the effect of cytoplasmic HDAC3 on post‐brain metastatic survival may become statistically significant." (PMID 32686908, 2020).
breast cancer (continued). "Strikingly, the decreased invasiveness was re-increased by the transient transfection of the shRNA-resistant HDAC3wt plasmid, but not by rshHDAC3Y321/331, strongly confirming that EGFR–c-Src mediated HDAC3 phosphorylation at Y321 and 331 was crucial for the invasion of breast cancer cells." (PMID 31430896, 2019). "Taken along with our previous results, HDAC3 phosphorylation by EGFR–c-Src may be involved in regulating the invasiveness of breast cancer cells through the modulation of its enzymatic activity." (PMID 31430896, 2019). "The relationship between HDAC3 and breast cancer has been recently reported." (PMID 31430896, 2019). "Apart from a study on HDAC1 and HDAC3 expression in breast cancer describing an overexpression of both isoforms, reports on expression patterns of distinct HDAC isoforms in tumour entities are sparse and most of the cohorts investigated were of a small sample size." (PMID 18212746, 2008). "Our results showed that the expression of HDAC1/HDAC2/HDAC3 increased significantly in the tumor tissues compared to the adjacent non‐neoplastic breast tissue, indicating that the three histone deacetylases play vital roles in the initiation and development of breast cancer." (PMID 32686908, 2020). "Herein, our studies first reveal that HDAC3 is closely related to the occurrence and development of brain metastasis in breast cancer patients, and moreover, the cytoplasmic expression of HDAC3 may play a more important role than nuclear expression in the metastatic process." (PMID 32686908, 2020). "Aside from EGFR-c-Src, HDAC3 may be critically involved in the malignant behavior of breast cancer." (PMID 31430896, 2019). "Finally, to confirm whether EGFR–c-Src-mediated HDAC3 phosphorylation was critical for the invasion of breast cancer cells, we performed rescue experiment using shRNA-resistant HDAC3 plasmids (rsh-HDAC3)." (PMID 31430896, 2019). "Collectively, these results indicated that SAHA might promote survivin protein degradation in part through decreasing the ubiquitination protection from Hsp90 via HDAC6 inhibition and increasing the expression of 26S proteasome via HDAC3 inhibition in breast cancer cells." (PMID 27065869, 2016). "Since IGFBP2 is itself a potential target for therapeutic intervention, and has been shown to inhibit the growth of breast cancer cells in vivo, we propose that since HDAC3 is involved in reducing expression of IGFBP2, HDAC inhibitors maybe a useful tool to treat patients with progressive disease." (PMID 26107517, 2015). "Chidamide, a selective inhibitor targeting HDAC1, HDAC2, HDAC3, and HDAC10, has been approved for treating relapsed/refractory peripheral T cell lymphoma and hormone receptor-positive, HER2-negative breast cancer after endocrine therapy." (PMID 41049003, 2025). "The inhibition of HDAC3 and HDAC6 promoted HDAC inhibitor-induced autophagy and viability reduction in breast cancer cells, including MCF-7 cells." (PMID 36831644, 2023). "We observed variations in the expression levels of HDAC1, HDAC2, HDAC3 and HDAC10 mRNAs targeted by chidamide among the ER+ breast cancer cell lines." (PMID 37445654, 2023). "XZ9002, the first HDAC3-specific PROTAC, effectively reduces HDAC3 in breast cancer cells and is formed by the linkage of VHL E3 ligase and an inhibitor of HDAC3." (PMID 36770884, 2023). "Studies have shown that OLE can reduce progression, invasion, and proliferation of breast cancer cells by suppressing the activity of both HDAC2 and HDAC3." (PMID 37764768, 2023). "HDAC3 phosphorylation, mediated by EGFR and c-Src, promoted the invasion of breast cancer cells, including MCF-7 cells." (PMID 36831644, 2023).
breast cancer (continued). "Oncomine data analysis revealed that most HDACs, including HDAC1, HDAC3, HDAC5, HDAC7, HDAC10, and HDAC11, are upregulated in luminal breast cancer subtypes." (PMID 35453496, 2022). "HDAC3 represses CREB3 mediated transcription and migration of breast cancer cells that are metastatic." (PMID 33167967, 2020). "HDAC3 selectively represses CREB3-mediated transcription and migration of metastatic breast cancer cells." (PMID 32571203, 2020). "In both MCF-7 and MD-MB-231 breast cancer cell lines, CREB3 binds specifically to Histone Deacetylase 3 (HDAC3)." (PMID 31334233, 2019). "HDAC3 can also bind to cAMP response element-binding protein (CREB) and decrease the migration potential of metastatic breast cancer cells." (PMID 30583572, 2018). "The effect of HDAC inhibitor, trichostatin A (TSA), on Nav1.5, nNav1.5, HDAC1, HDAC2, HDAC3, REST, MMP2 and N-cadherin gene expression and on cell motility and migration of the less metastatic human breast cancer cells, MCF-7, were investigated." (PMID 28785170, 2017). "Knockdown of either Xist or SPEN expression in breast cancer cells suppressed the expression of PHLPP1, a phosphatase in AKT dephosphorylation, and was correlated with increased HDAC3 recruitment to the PHLPP1 promoter." (PMID 27248326, 2016). "Based on these results, we propose that the phosphorylated GATA1 by PAK5 recruits more HDAC3/4 to the E-cadherin promoter, thus promotes transcriptional repression of E-cadherin, leading to the EMT of breast cancer cells." (PMID 25726523, 2015). "Meanwhile, we showed that phosphorylated GATA1 by PAK5 recruits more HDAC3/4 to promote transcriptional repression of E-cadherin, leading to the EMT of breast cancer cells." (PMID 25726523, 2015). "In breast cancer, high (IRS 9–12) nuclear expression of HDAC1, HDAC2 and HDAC3 was observed in 32.7%, 24.1% and 31.7% of cases, respectively." (PMID 23627572, 2013). "Enrichment difference analysis of the genes showing changes after OHT treatment revealed known breast cancer oncogenes such as HDAC3, UBE2C and CPSF7 among the depleted genes and reported breast cancer suppressors such as CSK, SPRED2 and TSC2 among the enriched genes." (PMID 38914552, 2024). "Our results are in line with the previously reported worse survival rate of cancer patients with overexpressing class I HDACs, especially HDAC1 and HDAC3 in lung cancers, HDAC2 in liver or breast cancers, and HDAC1/2/3 in ovarian cancers, gastric cancers, or sarcomas." (PMID 39063083, 2024). "Activated AR has been shown to cooperate with HDAC1, HDAC2, or HDAC3 to downregulate E-cadherin and promote the migration of non-metastatic breast cancer cells." (PMID 39000339, 2024). "In human breast cancer, HDAC1, HDAC2, and HDAC3 have been found to be differentially expressed." (PMID 38935814, 2024). "Furthermore, MDA-MB-231 and MCF-7 treated with combined concentrations of genistein and SFN resulted in the decreased expression of HDAC2, HDAC3, KLF4, and hTERT, suggesting the alterations of epigenetic mechanisms in breast cancer cells." (PMID 36765652, 2023). "SUMOylation of ERα mediated by SUMO1/sentrin/suppressor of Mif2-specific peptidase 2 (SENP2) promotes the recruitment of histone deacetylase 3 (HDAC3), which leads to the repression of estrogen-dependent and estrogen-independent proliferation of breast cancer cells." (PMID 35453496, 2022). "Increased expression of HDAC1, HDAC2, HDAC3 and HDAC6 are reported in several cancers including colon, prostate and breast cancer and inhibition of HDACs potentially could target proliferation, differentiation, angiogenesis, and migration." (PMID 33802026, 2021). "The downregulation of SEI-1, cyclin D2, and histone deacetylase 3 suggested that in addition to the identified effects of SFN against breast cancer prevention, it may also exert antitumor activities in established breast cancer cells." (PMID 31084542, 2019).
breast cancer (continued). "Our study also reveals that down-regulation of survivin gene transcription and protein stability by the inhibition of HDAC6 and HDAC3 might play important roles in both SAHA-induced autophagy and SAHA-reduced cell viability in breast cancer cells." (PMID 27065869, 2016). "However, it is interesting to see that down-regulation of HDAC3 (the second most selected target of SAHA) by siRNA also induced survivin acetylation and nuclear translocation in breast cancer cells." (PMID 27065869, 2016). "Therefore, it is possible that inhibition of HDAC6 and HDAC3 all contributed to the SAHA induced survivin acetylation, nuclear translocation, and the subsequent protein degradation in breast cancer cells." (PMID 27065869, 2016). "PAK5 phosphorylates the transcription factor GATA1 mainly at Ser161 and Ser 187, phosphorylated GATA1 recruits more HDAC3/4 to the promoter of E-cadherin and consequently suppresses the transcription of E-cadherin gene and promotes the EMT of breast cancer cells." (PMID 25726523, 2015). "In addition, HDAC2 and HDAC3 were shown to facilitate the inhibition of vascular endothelial growth factor (VEGF) signaling, which promotes angiogenesis to support tumor progression, in breast cancer cells in vitro." (PMID 40165290, 2025). "For example, in breast cancer cells, HDAC1–3 are inhibited by SFN to induce cell apoptosis; in skin cells, HDAC1–4 are regulated by SFN; in the cochlea, SFN inhibits HDAC2, 4, and 5; and in colon cancer models, SFN downregulated only HDAC3 to prevent DNA damage repair." (PMID 36006435, 2022). "Targeting HDAC3 also mimicked the effect of SAHA in up-regulating the expression and activity of proteasome, which might lead to the reduced protein stability of survivin in breast cancer cells." (PMID 27065869, 2016). "Interestingly, our TCGA data set analysis showed expression levels of PHLPP1, but not HDAC3, were decreased in breast cancer tissues compared to adjacent normal tissues." (PMID 27248326, 2016). "ThisPROTAC potently and selectively degraded HDAC3 (DC50 =0.042 μM, 14 h treatment) while sparing other HDAC isozymesin a triple-negative breast cancer cell line (MDA-MB-468) and a ER+ breast cancer cell line (T47D)." (PMID 40637413, 2025). "An additional analysis of HDAC1–3 expression for hormone receptor–based characterization of breast cancer also revealed significant alterations in expression of HDAC 1 and 2, but not HDAC3 across various subtypes." (PMID 31900196, 2020). "High expression of CSNK2B (p = 0.0041, HR = 1.37), GRPEL1 (p = 0.0200, HR = 1.29) and QARS (p = 0.0350, HR = 1.26) were corelated with worse prognosis in breast cancer patients, whereas CCND3, HDAC3, SH3BGRL3, SRM, and UBE2D4 were not correlated with OS." (PMID 31781497, 2019). "However, rshHDAC3Y328/331 did not rescue the invasion ability of breast cancer cells, indicating that EGFR–c-Src-mediated HDAC3 phosphorylation is involved in the invasion of breast cancer cells." (PMID 31430896, 2019). "Interestingly, down-regulation of HDAC3, but not other HDAC isoforms, by siRNA increased the expression of 26S proteasome in breast cancer cells." (PMID 27065869, 2016). "Therefore, quantitative real-time PCR was performed to determine whether HDAC2, HDAC3, and HDAC6 (but not HDAC1) can regulate survivin gene expression in breast cancer cells." (PMID 27065869, 2016).